CBX3 (chromobox 3)
Description:
Component of heterochromatin, which recognizes and binds histone H3 tails methylated at 'Lys-9', leading to epigenetic repression. Also recognizes and binds histone H1.4 methylated at 'Lys-26' (H1.4K26me). Excluded from chromatin when histone H1.4 is Simultaneously methylated at Lys-26 (H1.4K26me) and phosphorylated at Ser-27 (H1.4S27Ph). Involved in the formation of functional kinetochore through interaction with MIS12 complex proteins. Contributes to the conversion of local chromatin to a heterochromatin-like repressive state through H3 'Lys-9' trimethylation, mediates the recruitment of the methyltransferases SUV39H1 and/or SUV39H2 by the PER complex to the E-box elements of the circadian target genes such as PER2 itself or PER1 (By similarity). Mediates the recruitment of NIPBL to sites of DNA damage at double-strand breaks (DSBs).
Synonyms: HP1Hs-gamma; HP1gamma; HECH; HP1-GAMMA
Tractability: PROTAC: UniProt records ubiquitination sites on it; ubiquitination databases record sites on it; its protein half-life has been measured.
Target class: Epigenetic regulator; Reader; Methyl-lysine/arginine binding protein; Chromodomain
Gene: Protein-coding gene on chromosome 7 (26,201,162 to 26,213,607, forward strand). Ensembl gene ENSG00000122565.
Subcellular location: Nucleus
Subcellular location (Human Protein Atlas): Nucleoplasm; Nuclear bodies
Pathways (Reactome):
Gene expression (Transcription): ERCC6 (CSB) and EHMT2 (G9a) positively regulate rRNA expression; RNA Polymerase I Promoter Escape; Transcriptional Regulation by E2F6
Chromatin organization: ChAHP complex assembly
Gene Ontology:
Molecular function: enzyme binding; histone H1K26me1 reader activity; histone H1K26me2 reader activity; histone H3K9me2/3 reader activity; histone methyltransferase binding; identical protein binding; protein binding; protein domain specific binding; transcription coregulator binding; chromatin binding
Biological process: DNA damage response; heterochromatin formation; negative regulation of DNA-templated transcription; chromatin remodeling
Cellular component: chromatin; chromatin lock complex; chromosome, centromeric region; chromosome, telomeric region; euchromatin; heterochromatin; nuclear body; nucleoplasm; nucleus; RNA polymerase II transcription regulator complex; site of DNA damage; spindle; condensed chromosome, centromeric region; nuclear envelope; nuclear inner membrane; pericentric heterochromatin
Genetic constraint (gnomAD): Loss-of-function variants: 3 observed, 13.73 expected, observed/expected ratio (o/e) 0.22, 90% interval 0.098 to 0.56. The upper end of that interval is the gene's LOEUF score, 0.56, which puts it in group 2 of 6, group 1 being the genes least tolerant of losing a copy. Missense variants: 61 observed, 129.49 expected, observed/expected ratio (o/e) 0.47, 90% interval 0.38 to 0.58. Synonymous variants: 42 observed, 39.82 expected, observed/expected ratio (o/e) 1.05, 90% interval 0.82 to 1.36.
Homologues: Orthologues: dog CBX3 (100% identical), macaque CBX3 (100% identical), mouse Cbx3 (100% identical), rat Cbx3 (100% identical), pig CBX3 (99% identical), tropical clawed frog cbx3 (89% identical), zebrafish cbx3a (75% identical), Drosophila melanogaster HP1b (50% identical), Drosophila melanogaster HP1c (38% identical), Caenorhabditis elegans hpl-1 (34% identical), Caenorhabditis elegans set-31 (32% identical). Paralogues in human: CBX1 (71% identical), CBX5 (62% identical), CBX2 (30% identical), CBX6 (28% identical), CBX4 (28% identical), CBX8 (26% identical), CBX7 (23% identical), NPTXR (9% identical).
Diseases named in the same sentence as CBX3 in open-access papers:
CBX3 is named in the same sentence as 101 diseases in open-access papers, as found by Europe PMC text mining. Sharing a sentence is not in itself a finding about the gene and the disease. The quoted sentences say what the papers report.
colorectal cancer (21 papers, 2017 to 2024). A primary or metastatic malignant neoplasm that affects the colon or rectum. "Recently, CBX3 was revealed to be associated with lung cancer, osteosarcoma, gastric cardia adenocarcinoma and colorectal cancer." (PMID 31138312, 2019). "In colorectal cancer, the HP1γ protein encoded by chromobox 3 gene (CBX3), is overexpressed and associated with poor prognosis, while miR-30a is down-regulated." (PMID 29401683, 2018). "Interestingly, high IFNγ expression correlated with high STAT1 or CD274 expression in colorectal cancer, but high CBX3 expression was significantly associated with low expression levels of STAT1 or CD274." (PMID 38684864, 2024). "The fact that CBX3-PΨg is recurrent (found in 82.6% of the samples) may suggest that it might have an effect in the predisposition to colorectal cancer development." (PMID 35114952, 2022). "CBX3 appears as a potential target to enhance IFNγ-related therapeutic efficacy in UC and in colorectal cancer." (PMID 38684864, 2024). "We then examined clinical data from colorectal cancer (CRC) patients to investigate the potential antagonist effect of CBX3 and IFNγ on the expression of STAT1/PD-L1 in CRC." (PMID 38684864, 2024). "Our further clinical analysis revealed also the antagonist effect between IFNγ and CBX3 in colorectal cancer on STAT1/PD-L1 expression." (PMID 38684864, 2024). "Our work identifies an interplay between CBX3 and IFNγ signaling that leads to regulation of the immune response in colon epithelium and of chemo-resistance of colorectal cancer." (PMID 38684864, 2024). "For example, in humans, NCAPG is regulated by chromobox protein homolog 3 (CBX3) transcription, which activates Wnt/β-catenin signaling and promotes colorectal cancer progression." (PMID 38473754, 2024). "Recent evidence from studies has shown that CBX3 is upregulated in colorectal cancer in human, which stimulated cell proliferation by candidly modulating CDKN1A through methylation of histone H3K9 at its promoter." (PMID 35573019, 2022). "Aberrant expression of CBX3 has been detected in several cancer types such as pancreatic cancer, osteosarcoma, colorectal cancer, breast cancer, and liver cancer." (PMID 35210369, 2022). "CBX3 is upregulated in various types of cancer, including lung cancer, osteosarcoma, liver cancer, and colorectal cancer." (PMID 34785774, 2022). "For cancers in the digestive system, the relationship between gastric cancer, hepatocellular carcinoma, colorectal cancer and CBX3 were analyzed, besides PAAD." (PMID 35172803, 2022). "The expression of CBX3 was elevated in human colorectal cancer, prostate cancer, breast cancer and pancreatic cancer." (PMID 34722422, 2021). "In terms of the regulation of gene expression by microRNA, mir-30a, mir-30b, and mir-320a exert anticancer effects by inhibiting CBX3 expression in colorectal cancer and esophageal squamous cell carcinoma." (PMID 33273987, 2020). "Previous studies have reported that CBX3 is upregulated in a variety of cancer tissues, covering colorectal cancer, breast cancer, hepatocellular carcinoma, and lung cancer." (PMID 33273987, 2020). "Knockdown of CBX3 increased p21 expression, resulting in slower proliferation of colorectal cancer cells." (PMID 31138312, 2019). "The miR-30a/CBX3/p21 axis is proposed to regulate the development of colorectal cancer and to be a prognostic and therapeutic target." (PMID 31138312, 2019). "Recent studies show that CBX3/HP1γ is upregulated in human colorectal cancer and that it promotes cell proliferation by directly regulating CDKN1A via methylation of histone H3K9 on its promoter." (PMID 31375643, 2019). "CBX3 expression was increased in human colorectal cancer and promoted in vitro and in vivo proliferation of the tumor cells, which was associated with its regulation on CDKN1A in colorectal cancer cells." (PMID 29903985, 2018).
colorectal cancer (continued). "Studies from Liu et at showed that CBX3 was over-expressed in human colorectal cancer and it promoted cell proliferation of colorectal cancer cell lines by directly regulating CDKN1A in a manner associated with methylation of histone H3K9 on its promoter." (PMID 30481161, 2018). "The role of CBX3 has been studied in various types of human cancers, such as breast cancer, non-small cell lung cancer, colorectal carcinoma and prostate cancer." (PMID 29903985, 2018). "Our findings indicate that CBX3 could antagonize IFNγ, CBX3 thus becomes a potential target to improve colorectal cancer treatment." (PMID 38684864, 2024). "Moreover, CBX3 K10la levels were obviously increased in pancreatic and colorectal cancer cells compared with normal epithelial cells." (PMID 39018247, 2024). "Currently, the expression of CBX3 was found to increase in non-small cell lung cancer, prostate cancer, colorectal cancer, and breast cancer, which may predict the poor prognosis of patients." (PMID 35172803, 2022). "Moreover, the additional analysis results in the ONCOMINE database further confirmed that CBX3 is highly expressed in breast cancer, cervical cancer, lung cancer, kidney cancer, colorectal cancer, and ovarian (P < 0.01), compared with normal controls." (PMID 35172803, 2022). "Moreover, miR-30a targeted CBX3/HP1γ invitro and invivo to specifically inhibit the growth of colorectal cancer in mouse xenograft models." (PMID 31375643, 2019). "Recently, although gene expression assays have revealed that CBX3 is linked with lung cancer, osteosarcoma, gastric cardia adenocarcinoma and colorectal cancer, among other diseases, the specific mechanisms by which CBX3 promotes cancer progression are poorly understood." (PMID 28193906, 2017). "Moreover, the higher expression of CBX3 is detected in poorly differentiated colorectal cancer tissues and the overall patient survival rate was significantly decreased." (PMID 28193906, 2017). "Altogether, this work identifies a new antagonist interplay between CBX3 and IFNγ signaling to regulate colon immune response and chemosensitivity of colorectal cancer, which highlights CBX3 as a potential target to improve the treatment of UC and colorectal cancer." (PMID 38684864, 2024). "Furthermore, CBX3 promotes colorectal cancer cell proliferation and tumorigenesis." (PMID 31138312, 2019). "Moreover, miR-30a could target CBX3 in vitro and in vivo to specifically inhibit the growth of colorectal cancer in mouse xenograft models." (PMID 30481161, 2018). "CBX3 is highly expressed in lung adenocarcinoma (LUAD), pancreatic cancer (PACA), colorectal cancer (CRC), PRCA, non-small-cell lung cancer (NSCLC), and tongue squamous cell carcinoma (TSCC)." (PMID 33344640, 2020). "Further study demonstrated that CBX3 can suppress the transcription of CDK6 and p21, the negative cell cycle regulators, and promote proliferation of colorectal cancer cells." (PMID 29903985, 2018). "Significant up-regulation of CBX3 had been found in a variety of cancers, including lung adenocarcinoma (LUAD) and non-small cell lung cancer (nSCLC), tongue squamous cell carcinoma (TSCC), and colorectal cancer." (PMID 30481161, 2018). "CBX3 can inhibit the transcription of negative cell cycle regulators CDK6 and P21 and promote the proliferation of colorectal cancer cells." (PMID 35573019, 2022).
lung carcinoma (20 papers, 2017 to 2024). "The following subsections describe the role of CBX3 in key cancer-associated pathways and aim to shed light on its mechanistic role in lung cancer progression." (PMID 39272883, 2024). "The identification of CBX3 as a biomarker for lung cancer, combined with its significant association with immunity, reinforces its potential as a viable therapeutic target within the PI3K-AKT pathway." (PMID 39272883, 2024). "A previous meta-analysis demonstrated that high CBX3 expression was associated with poor prognosis in patients with lung cancer, tongue squamous cell carcinoma, digestive cancer, and urinary cancer." (PMID 34785774, 2022). "In patients with nonsmall cell lung cancer, CBX3 expression has a significant correlation with EGFR mutations." (PMID 33273987, 2020). "CBX3/HP1γ is also one of the most frequently over-expressed histone reader proteins in human lung cancer, and high CBX3/HP1γ mRNA levels are associated with poorer prognosis." (PMID 31375643, 2019). "Notably, an elevated expression of CBX3 in lung cancers linked to smoking is often caused by genetic changes, such as an increase in the number of copies of the gene, as well as in epigenetic dysregulation." (PMID 39272883, 2024). "Additionally, targeting CBX3 holds the potential for personalized therapy options for lung cancer patients who exhibit specific mutations impacting the Wnt pathway." (PMID 39272883, 2024). "Understanding the exact molecular mechanisms through which KRAS mutations influence CBX3 function, and vice versa, could open new avenues for targeted therapies in lung cancer patients harboring these mutations." (PMID 39272883, 2024). "In lung cancer, CBX3 mRNA expression was increased and was associated with a shorter survival time." (PMID 35155439, 2022). "Additionally, understanding the structural nuances of CBX3 and its transcript variants can provide deeper insights into its regulatory complexity and functional diversity, thereby paving the way for innovative strategies in lung cancer therapy." (PMID 39272883, 2024). "Remarkably, CBX3 is involved in several signaling pathways, critical for cell survival, proliferation, and differentiation, and plays a dominant role in lung cancer." (PMID 39272883, 2024). "Various methodologies, including quantitative PCR and immunohistochemistry, have been employed to measure CBX3 expression levels, revealing a compelling correlation between elevated CBX3 levels and poor prognosis in lung cancer patients." (PMID 39272883, 2024). "Recent studies have highlighted the dysregulation of CBX3 expression in lung cancer tissues compared to adjacent normal tissues, suggesting its potential role as a biomarker for prognosis and treatment response." (PMID 39272883, 2024). "Addressing the mechanisms by which CBX3 contributes to lung cancer progression, particularly its involvement in cell proliferation, apoptosis regulation, and the modulation of key oncogenic pathways, will open novel avenues for therapeutic intervention." (PMID 39272883, 2024). "Although the precise mechanism by which CBX3 contributes to lung cancer is far from being completely elucidated, some evidence points to its potential interaction with EGFR signaling." (PMID 39272883, 2024). "The therapeutic potential of targeting CBX3 in lung cancer is underscored by its overexpression in NSCLC and its association with epigenetic modifications and cell differentiation." (PMID 39272883, 2024). "Combining CBX3 inhibitors with other therapeutic agents represents a multipronged strategy to enhance the efficacy of cancer treatments, including lung cancer." (PMID 39272883, 2024). "Building on the evidence of CBX3 overexpression in lung cancer tissues, the integration of Notch signaling pathway inhibitors with CBX3 targeting represents a promising strategy for therapeutic intervention." (PMID 39272883, 2024).
lung carcinoma (continued). "Examining the relationship between CBX3 and ErbB receptors would be useful to uncover potential therapeutic targets to mitigate the aggressiveness of lung cancer." (PMID 39272883, 2024). "Among family members, CBX3 is a complex protein involved in aberrant epigenetic mechanisms that drive lung cancer progression." (PMID 39272883, 2024). "The role of CBX3 in lung cancer progression is intricate and multifaceted, particularly in its interactions with ErbB receptors." (PMID 39272883, 2024). "In the context of lung cancer, the involvement of CBX3 in the Notch signaling pathway is intricate and diverse, underscoring the complex interplay between chromatin organization and signaling pathways in cancer progression." (PMID 39272883, 2024). "This highlights the necessity for further research into CBX3 inhibitors as a means to develop more effective treatments for lung cancer." (PMID 39272883, 2024). "To summarize, CBX3 functions as a transcriptional regulator in the Wnt/β-catenin signaling pathway, impacting the advancement of lung cancer by controlling gene expression, facilitating cell cycle progression, and interacting with pathways such as RAC1." (PMID 39272883, 2024). "Overexpression of CBX3 has also been observed in many malignancies such as lung cancer, gastric cancer, and tongue squamous cell carcinoma." (PMID 34395271, 2021). "In the future, experimental studies regarding the molecular mechanism of CBX3 in lung cancer will be performed." (PMID 32894652, 2020). "Some studies have indicated that CBX3 expression is upregulated in many human cancers, such as cervical cancer, breast cancer and lung cancer 27, 32-34." (PMID 32742466, 2020). "In this context, the overexpression of the CBX3 gene is associated with a negative outlook, suggesting its potential role as a target for treatment and a useful indicator of lung cancer prognosis." (PMID 39272883, 2024). "CBX3 has a significant effect on the KRAS signaling pathway in lung cancer." (PMID 39272883, 2024). "Current strategies aimed at inhibiting CBX3 activity in lung cancer are being explored." (PMID 39272883, 2024). "As research continues to uncover the multifaceted roles of CBX3 in lung cancer, there is a growing interest in its integration into personalized medicine approaches and the identification of challenges and opportunities for the therapeutic targeting of CBX3." (PMID 39272883, 2024). "However, the precise mechanisms by which CBX3 contributes to the development and progression of lung cancer, including its involvement in different signaling pathways, have not been thoroughly examined and require additional research." (PMID 39272883, 2024). "Enrichment analysis seems to support this hypothesis, but further research is needed to establish the specific role of CBX3 in this pathway in lung cancer." (PMID 39272883, 2024). "The mode of action of CBX3 in lung cancer involves its function as a transcriptional regulator." (PMID 39272883, 2024). "We analyze the main upstream regulators of CBX3 expression and activity and describe the various pathways involving CBX3, highlighting its differential mechanisms of action as well as its significance as a potential therapeutic biomarker in lung cancer." (PMID 39272883, 2024). "Inhibiting CBX3 could have profound implications for the MAPK pathway in lung cancer cells, primarily due to the intricate network of interactions that CBX3 maintains with various signaling pathways." (PMID 39272883, 2024).